CD4 (CD4 molecule)
Diseases named in the same sentence as CD4 in open-access papers (continued):
Sharing a sentence is not in itself a finding about the gene and the disease.
tumor (continued). "By analysing the B16-OVA tumour infiltrate, we found enhanced frequency of IL-9-producing CD4 tumour-infiltrating lymphocytes (TILs)." (PMID 28916785, 2017). "Further, several researchers have shown the utility of the full length tetanus toxin fragment C protein (Frc), with known promiscuous epitopes that widely bind with murine and human MHC class II molecules to induce viable anti-tumor CD4+ T-cell response." (PMID 28304339, 2017). "Tumor infiltration of T cells (CD3+CD4+ and CD3+CD8+), NK cells (CD161+) and B cells (CD45R) was not different between LD and LL." (PMID 28874144, 2017). "The results demonstrated that the T-cell subsets resident within GC is different from that in paraneoplastic tissue and blood, and the increase in Tim-3+ PD-1+ CD4+ T-cells in tumor tissues was found to correlate with the clinical cancer stage and Tregs." (PMID 29213216, 2017). "The results of our study showed that SBE treatment significantly decreased the amount of CD4+IL-17+ (Th17) cells in the tumor tissue." (PMID 28086772, 2017). "In contrast, injection of recombinant TGF-β into the tumour increased both IL-9-eGFP+ CD4+ T cells and Irf8 expression in CD4+ T cells in vivo." (PMID 29233972, 2017). "We have demonstrated previously, along with others that GITR-triggering with a GITR mAb can enhance T cells via costimulation and reduce the number of CD4 Tregs in the tumor." (PMID 29312597, 2017). "This apparently contradictory finding of a ‘double-edged immunological sword’ is conceptually interpreted based on the central role of CD4+ cells in the anti-tumor response." (PMID 28977830, 2017). "Specifically, they tested the ability of tumor-specific CD4 T cells polarized into TH9 cells or other effector CD4 T cell subsets to prevent tumor outgrowth in B16 tumor-bearing mice upon adoptive transfer." (PMID 27832300, 2017). "By immunochemistry and ELISA, we found that the spleen and tumor tissues in DC-VEC group had increased number of activated CD4+ and CD8+ T cells and cytotoxicity cytokines of IFN-γ and IL-4, with decreased secretion of immune suppressive cells and cytokines." (PMID 28978039, 2017). "As the important components of adaptive immune system, CD4+ T cell subsets initiate different immune responses, and the balance between antitumor immunity and tumor immune evasion determines the direction of the malignant process." (PMID 29383114, 2017). "Like those in healthy subjects, tumor-derived PD-1+CD4+ effector cells displayed significantly less proliferation but retained the ability to produce inflammatory cytokines." (PMID 28880903, 2017). "Combined, these data indicate that CD4CAR NK-92 cell anti-tumor cytotoxicity is dose-dependent, of rapid onset and is specific to CD4+ cells." (PMID 29348865, 2017). "Splenic Ly6Ghi cells from MOC1 tumor-bearing mice suppressed CD3/28 stimulated CD4+ and CD8+ T-lymphocyte proliferation in a dose-dependent fashion." (PMID 28915554, 2017). "In some cases, OX40 ligation has been shown to suppress the tumor suppressor activity of FoxP3+ CD25+ CD4+ regulatory T cells (Tregs)." (PMID 28848246, 2017). "In comparing the brain, DLN, and spleen, we determined that the CD4+ CD25+ populations have more fatty acid uptake within the tumor microenvironment: 31% ± 2.0%, DLN: 5% ± 0.5% and spleen: 6% ± 0.6%." (PMID 28724939, 2017). "Tregs would increase in tumor site or be induced into CD4+, CD25+ T cells by tumor-associated DCs (dendritic cells) and FOXP3 gene played a critical role in Tregs’ differentiation, development and maintenance of function during this process." (PMID 28029650, 2017). "In this study, the expression of FOXP3 was detected in HCC cell lines and tumor tissues, although the expression was obviously lower than CD4+CD25+ cells." (PMID 28903735, 2017). "They found that tumor-infiltrating CD4+ T cells were skewed toward Treg (FoxP3+, forkhead box P3) and T helper 17 (Th17) phenotypes rather than Th2 phenotype." (PMID 28292326, 2017).
tumor (continued). "DC vaccination combined with the transfer of CD4+ T cells and lymphodepletion significantly inhibited tumor progression." (PMID 28854279, 2017). "This novel vaccine elicited an integrated and multiepitopic immune response with persistent CD8+ and CD4+ stimulation in different tumour models and will be soon investigated in human GI models." (PMID 28758114, 2017). "In contrast, Lm-E7 was shown to be an effective tumor immunotherapy in mice depleted of CD4+ T cells." (PMID 28588899, 2017). "In our study, we have found that gene expression levels of CD8 in both tumor and tumor-near stroma compartments, and of CD4 only in the tumor compartment, were correlated with better outcomes." (PMID 27463005, 2016). "This discrepancy can be explained by the fact that CD4+ TILs form a heterogeneous population of cells with different phenotypes and even with opposing actions in the tumor microenvironment." (PMID 27463005, 2016). "It is widely accepted that CD8+ T cells are instrumental for an anti-tumor response, but the involvement of CD4+ T cells is far less clear and potentially disruptive." (PMID 27777771, 2016). "Because MHC molecules govern interactions between tumor cells and CD4 and CD8 T cells, early studies examined the effects of ErbB/HER inhibition on MHC expression." (PMID 27729860, 2016). "We developed DC-tumor FCs strategies to induce efficient antitumor immune responses mediated by antigen-specific CD4+ and CD8+ T cells and to break T cell tolerance to TAAs." (PMID 27240347, 2016). "Treg constitute an important fraction of tumor-infiltrating CD4+ T cells and inhibit tumor-reactive T cells either by direct cell contact or through TGF-β and IL-10 production." (PMID 28003994, 2016). "Another evidence for the importance of tumor-infiltrating CD4+ T cells in MSI CCR comes from a histological study." (PMID 27060000, 2016). "SCIB1 vaccination was associated with increased infiltration of CD4 and CD8 T cells within the tumor but was also associated with upregulation of PD-L1 within the tumor environment." (PMID 27825115, 2016). "In sharp contrast, differentiation of CD4+ T cells into IL-10-secreting regulatory T cells inhibits adaptive immune responses and thereby promotes tumor immune evasion." (PMID 27853652, 2016). "Experimental animals showed a strong cytotoxic response against tumor, with activation of CD4+ and CD8+ T cells and splenocytes." (PMID 27462315, 2016). "APCs particularly dendritic cells (DC) sample antigens from tumor cells and present antigens to CD4+ T cells via the MHC class-II pathway or to CD8+ T-cells via cross presentation or cross priming." (PMID 27340370, 2016). "In particular, LAG-3 is important for the suppressive functions of CD4+ Tregs in autoimmune responses, and for maintaining tolerance to self and tumor antigens via dampening the activity of antigen-specific CD8+ T cells." (PMID 27835902, 2016). "We demonstrated that TIM-3 was upregulated in CD4 and CD8 T cells from anti-PD-1-resistant EGFR and Kras mutated tumours as compared with untreated tumours." (PMID 26883990, 2016). "Using bioluminescence imaging to measure tumor burden, we have observed similar results with these two tumor doses showing that GzmB−/− CD4+CD25− Tcon cells are less effective than WT CD4+CD25− Tcon cells in controlling tumor growth." (PMID 27774524, 2016). "Alternatively, it has been shown that increased brain migration of adoptively transferred CD8 T cells can be obtained by co-infusion of CD4 T cells specific for the same tumor antigen and bearing the Th1 phenotype." (PMID 28003994, 2016). "Nevertheless, patients with advanced tumor stage, metastasis, and pathological tumor fracture displayed significantly higher Tim‐3 on both CD4+ T cells and CD8+ T cells than those with early tumor stage, without metastasis and pathological tumor fracture." (PMID 27516959, 2016).
tumor (continued). "Multiple previous studies have shown that tumor-specific CD4+FoxP3 Tregs express multiple inhibitory receptors, including PD-1 and TIM3, which likely reduce the capacity of T cells in the tumor microenvironment for proliferation and cytokine production." (PMID 26943572, 2016). "Most importantly, VV-FCU1 treatment modified the CD8+/CD4+ Treg ratio in the tumor microenvironment." (PMID 27057460, 2016). "TOX is a transcription factor with a role in the development of CD4+ T cells, including downstream effects on the expression ofRUNX 3, a well-known tumor suppressor gene." (PMID 27540476, 2016). "Our flow cytometry and IHC results indicate a significant increase in CD69+CD4+ cells in the tumor cell areas." (PMID 27999289, 2016). "The emphasis on a Th1 CD4 T cell bias has been considered ideal for generating anti-tumor CD8 T cells." (PMID 27472363, 2016). "In situ delivery of RdB/IL12/shVEGF to tumor tissues resulted in massive infiltration of differentiated CD4+ T cells, CD8+ T cells, natural killer cells, and dendritic cells to tissues surrounding the necrotic region of tumor." (PMID 27821803, 2016). "We found that a significantly higher frequencies of IL-10-expressing B cells and significantly lower frequencies of CD4+ cytotoxic T cells in the tumor, compared to their counterparts in peripheral blood." (PMID 27136203, 2016). "Worthy to be noticed, 6 tumors in the current series demonstrated a CD4-positive phenotype, characterized by a diffuse and intensive positive staining for this marker in almost all the tumor cells." (PMID 27564014, 2016). "CD4+ and CD8+ T cell counts, either in blood or tumor site, were both negatively associated with the final tumor weight." (PMID 27409425, 2016). "The ubiquitin-modifying enzyme A20, an important negative feedback regulator of NF-κB, impairs the expansion of tumor-specific CD8+ T cells but augments the proliferation of autoimmune CD4+ T cells." (PMID 28004776, 2016). "An increase in CD4+ T cells was seen initially followed by a CD8+ T cell increase until reaching a peak at day +38 after tumor injection." (PMID 27610392, 2016). "Recent studies have shown that IDH1 (R132H) represents an immunogenic tumor antigen recognized by CD4+IFN-γ-producing T cells in patients." (PMID 27738332, 2016). "We analyzed CD4+ T cells, macrophages and granulocytes in tumor, which are reported to be responsible for the anticancer ability of S. enterica." (PMID 27835896, 2016). "CD4+Th17, a subset of CD4+ T cells, is an additional type of immune suppressive cell that also infiltrates tumors and correlates with tumor progression." (PMID 27341128, 2016). "On multivariate analysis increased levels of CD4+ (p = 0.017) and CD8+ TILs (p = 0.005) were associated with significant local tumour regression and lymph node downstaging, respectively." (PMID 27020682, 2016). "Tumor-infiltrating immune cells including CD4+ T, CD8+ T, NK cells as well as macrophages were increased in IL-2C-treated mice than controls (P < 0.05)." (PMID 26772545, 2016). "Survival analyses indicated that patients with high CD4 expression in the tumor compartment, dichotomized according to the median of its relative expression, had improved PFS (37.8 vs. 23 months, p = 0.042) and OS (81.2 vs. 42.9 months, p = 0.018)." (PMID 27463005, 2016). "Analysis of tumor-infiltrating lymphocytes using immunohistochemistry in tissue sections revealed significantly higher number of both CD4+ and CD8+ lymphocytes in pTa-pT1 tumors than in more advanced cancers." (PMID 26862849, 2016). "Loxoribin, a TLR7 ligand, inhibited tumor growth in xenograft models of colon and lung cancers, and these anti-tumor effects were mediated by increased CD4+T cell proliferation and reversal of Treg-mediated immunosuppression via dendritic cells (DCs)." (PMID 27708223, 2016).
tumor (continued). "In conclusion, the present results unequivocally demonstrate the ability of CD4+ T cells specific for a secreted tumor antigen to eliminate MHC II-negative tumor cells." (PMID 27626487, 2016). "Tumor cells escape immune surveillance by creating an immunosuppressive microenvironment, which includes the recruitment or generation of CD4+FOXP3+ Treg cells and/or conversion of effector T cells into Treg cells." (PMID 28123897, 2016). "CD4+ Th17 cells play a dynamic role in tumor immunity though there are opposing reports regarding its function." (PMID 27120805, 2016). "In summary, our results provide evidence that indirect display of a secreted tumor antigen on infiltrating macrophages is sufficient for killing of MHCIINEG tumor cells by CD4+ T cells." (PMID 27626487, 2016). "T-reg also negatively regulate anti-tumor immunity to facilitate tumor growth, and depletion of total CD4+ T cells improves tumor immunity with effective tumor rejection." (PMID 27136535, 2016). "PD-L1 expressions in tumor cells (TCs) and TIICs, as well as infiltration of lymphocytes (CD4+, CD8+, FOXP3+, and PD- 1+) and macrophages (CD68+ and CD204+), were evaluated." (PMID 27322149, 2016). "IL-35-positive cells were primarily lymphocytes in both tumors and tumor-adjacent tissues, and IL-35 was especially highly expressed in CD4+ T cells." (PMID 27682874, 2016). "TADCs sorted from LLC tumours or naive splenic cDCs were co-cultured with CellTrace-labelled TCR transgenic CD8+ OT-I T cells or CD4+ OT-II T cells in the presence of OVA." (PMID 28008905, 2016). "DCs capture necrotic tumor cells, migrate to lymph nodes, and present tumor antigens (TAs) to naïve CD4+ T cells leading to their differentiation in effector CD4+ T cells, development of TA-specific CD8+ T cells, and their expansion." (PMID 28018902, 2016). "CD19+B cells isolated from tumors present a considerably greater suppressive effect on CD4+T-cell proliferation in comparison with the cells isolated from the spleen of tumor-bearing or non-tumor-bearing animal models." (PMID 27331871, 2016). "The number of CD4+ cells was initially higher then increased after radiation in the Axl Cr#1 tumours." (PMID 28008921, 2016). "We also noted a modification of the tumor microenvironment caused by an increased infiltration of CD3+ T lymphocytes (mainly CD8+ T lymphocytes) and a decreased proportion of CD4+ Tregs in tumor bearing kidneys as a result of VV-FCU1 oncolytic virotherapy." (PMID 27057460, 2016). "We further determined that L-selectin loss on splenic CD4+ and CD8+ T cells correlated temporally with the extent of MDSC expansion which varied among different murine tumor types." (PMID 27929373, 2016). "If LPS was given to mice after ACT, it increased the ratio of infused CD8+ T cells to host CD4+ T cells in the tumor of mice." (PMID 26885368, 2016). "Tumor-specific B cells reduced the number of tumor-reactive CD4+ T cells in secondary lymphoid tissues and the tumor itself, but had surprisingly little effect on the CD4+ T cell-derived cytokine profile." (PMID 27121060, 2016). "First, we co-cultured purified CD4+ or CD8+ TILs together with irradiated MB49 tumour cells and splenic dendritic cells (DCs) to evaluate production of tumour antigen-specific effector molecules by TILs." (PMID 27498556, 2016). "Where there is some sharing of MHC class I molecules, the alloreactive CD4+ T cell response provides potent T cell help for the generation of CD8+ CTL responses to tumor peptides presented by the shared HLA class I molecules." (PMID 27240347, 2016). "In a CT26 tumor model, GITR agonist rendered CD4+ T cells resistant to suppression and capable of tumor control, as well." (PMID 27242798, 2016). "Tumor-specific CD4+ effector T cells contribute to tumor eradication either via direct tumor cell killing or via the activation of macrophages at tumor sites." (PMID 26741508, 2016).
tumor (continued). "While the majority of the current ACT are focused on using CD8+ cytotoxic T lymphocytes (CTL), others have shown that the presence of tumor-reactive CD4+ T helper (Th) cells can greatly enhance the anti-tumor activity of CD8+ CTL." (PMID 27588200, 2016). "By co-transferring CD4+ T cells and B cells into tumor-bearing immunodeficient hosts, we determined the effects of B cell antigen presentation and antibody production on tumor protection and the anti-tumor CD4+ T cell response." (PMID 27121060, 2016). "The processed tumor-associated antigens are then presented by MHC class II and MHC class I molecules on the APC to the antigen-specific T cell receptor on CD4+ T cells or CD8+ T cells, respectively." (PMID 28116316, 2016). "The immunological response against the tumour was examined by immunohistolabelling of CD4 and CD8 on days 11, 14, and 21 after cell transplantation (n = 9)." (PMID 26763872, 2016). "Longitudinal analyses of tumor-infiltrating lymphocytes revealed a primary adaptive T cell response involving both CD4+ and CD8+ T cell subsets." (PMID 27610392, 2016). "The CD4+ T regulatory cells (Tregs) expressing FoxP3 promote tumor progression by inhibiting the NK and T cell functions." (PMID 27044404, 2016). "This suggests that SCIB1 alone and in combination with PD-1 blockade enhances CD8 and CD4 T cell infiltrate into the tumor environment." (PMID 27825115, 2016). "The use of whole tumour lysate with its vast amount of characterized and uncharacterized T-cell epitopes available for activating CD4+ T helper and CD8+ cytotoxic lymphocytes simultaneously offers distinct advantages in tumour vaccine preparation." (PMID 26795765, 2016). "With the loss of MDSCs, splenic CD4+IFNγ+ cells and CD8+IFNγ+ cells were accordingly increased accompanied by recovery of lysis against 4T1 tumor cells in curcumin-fed tumor bearers." (PMID 27405665, 2016). "In conclusion, we have demonstrated that high levels of Tregs among tumor-infiltrating CD4+ T cells were favorable, but an increased proportion of MDSCs was an adverse independent prognostic factor in GC." (PMID 26799288, 2016). "Spleens from tumor-bearing mice contain both effector (CD4+ and CD8+) and regulatory T cells (Tregs)." (PMID 27959896, 2016). "Foxp3+CD4+ T cells from the tumor environment show upregulation of cell-surface markers, including CTLA4, TIM3, and PD1, as well as a variety of chemokine receptors and suppressive cytokines." (PMID 27999575, 2016). "Specific activation of naive tumor-specific T lymphocytes by DCs is required to generate an army of effector CD8+ and CD4+ T cells that can effectively eliminate tumor cells." (PMID 26741508, 2016). "IL-35 expression was assessed using immunofluorescence double staining and was found to be expressed mainly in CD4+ T cells in tumor and tumor adjacent tissues." (PMID 27682874, 2016). "TGF-β also mediates the production of mitogenic growth factors, which stimulate tumor cell proliferation and survival, and stimulates the conversion of CD4+CD25- T cells to CD4+CD25+Foxp3+ regulatory T-cells, which suppresses host immune surveillance." (PMID 27863384, 2016). "In contrast, administering LPS after ACT potentiated the antitumor effectiveness of the regimen, thereby supporting the expansion of transferred tumor-specific CD8+ T cells over host CD4+ T cells." (PMID 26885368, 2016). "Interleukin 17A (IL-17A), a pro-inflammatory cytokine secreted by CD4+ Th17 cells, triggers tumor cells to produce interleukin 6 (IL-6), which in turn activates STAT3-dependent survival and angiogenesis." (PMID 27341128, 2016). "We examined the correlation between IL-10-expressing B cells and CD4+ T cells in the resected tumor." (PMID 27136203, 2016). "Further IHC data with tumor tissues indicated that, the tumor group had a higher number of CD4+ T cells, whilst the number of CD8+ T cells was higher in the treatment group." (PMID 27669687, 2016).